NPC1 (NPC intracellular cholesterol transporter 1)
Diseases named in the same sentence as NPC1 in open-access papers (continued):
Sharing a sentence is not in itself a finding about the gene and the disease.
liver disease (15 papers, 2010 to 2025). "Therapeutic approaches showed that both the combination therapy and HPβCD monotherapy ameliorate NPC1 liver disease symptoms by causing a reduction of hepatic lipids." (PMID 31500175, 2019). "In both human and mouse with a mutation in NPC1, the liver represents the highest rate of sterol accumulation, which forms a basis for the development of liver disease." (PMID 31500175, 2019). "This liver disease likely underlies the significant loss of npc1 mutant fish immediately after the larval stage." (PMID 30135069, 2018). "Liver disease has been shown to be associated with the most severe, neonatal form of NPC1, and it is the most common cause of death in neonatal-onset NPC1 patients." (PMID 30135069, 2018). "It would be useful to investigate a cohort of NPC1 mutation carriers to help determine whether there is an increased risk of infantile liver disease or adult-onset neurological or metabolic problems in these patients." (PMID 34828443, 2021). "However, the deficiency of Npc1 not only affects the brain but also induces additional systemic pathologies that include liver disease, splenomegaly and gastrointestinal inflammation." (PMID 31605022, 2019). "Maternal serum AFP levels taken as part of the routine pregnancy screen were within normal limits in all examined cases, implying that the liver disease in NPC1 probably begins postnatally." (PMID 35455589, 2022). "It is possible that the reduced weight is secondary to the more severe liver disease phenotype in the Mgat5−/−:Npc1−/− mice." (PMID 35563467, 2022). "The NPC1 zebrafish manifest both the early liver disease and later-onset neurological disease characteristic of NPC1." (PMID 30135069, 2018). "In the present study, we evaluated the effects of GdCl3 on NPC liver disease and we compared them with a genetic rescue of NPC1 protein in hepatocytes in vivo, which was previously shown to be sufficient to decrease liver pathology." (PMID 30441844, 2018). "Here, we studied the consequences of gadolinium chloride (GdCl3) treatment, a well-known Kupffer/foam cell inhibitor, at late stages of NPC liver disease and compared it with NPC1 genetic rescue in hepatocytes in vivo." (PMID 30441844, 2018). "Our npc1 mutant zebrafish model replicates both the early-onset liver disease and the delayed-onset neurological disease seen in human patients." (PMID 30135069, 2018). "Although the neonatal NPC1 liver disease can be fatal, the natural history of NPC1 is that the cholestatic liver disease often appears to resolve." (PMID 30135069, 2018). "We injected three mice with NPC1-specific antisense oligonucleotides (ASOs) twice a week for 15 weeks to induce NPC liver disease and found undetectable levels of IL-6 (<4 pg/ml)." (PMID 20886067, 2010). "However, Mgat5−/−:Npc1−/− had significantly higher levels of AST levels compared to Mgat5+/+:Npc1−/− mice, suggestive of a more severe liver disease phenotype." (PMID 35563467, 2022). "Both Mgat5−/−:Npc1−/− (n = 9) and Mgat5+/+:Npc1−/− (n = 5) mice exhibited generally elevated levels of these enzymes in their serum compared to the control mice (Mgat5+/+:Npc1+/+ (n = 8), and Mgat5−/−:Npc1+/+ (n = 10)), suggestive of liver disease in both groups at this age." (PMID 35563467, 2022). "Nevertheless, both therapeutic strategies ameliorated NPC1 liver disease symptoms." (PMID 29587349, 2018). "This NPC1 model thus replicates the early-onset liver disease seen in many NPC1 patients." (PMID 30135069, 2018). "When considered in light of the accompanying clinical study these data strongly suggest that whereas UDCA has potential as an adjunctive therapy to treat residual liver disease in NPC patients, CA is contraindicated due to acute hepatotoxicity that is most pronounced in an NPC1 deficient background." (PMID 29062912, 2017). "Altered P450 metabolism may also explain an intriguing observation regarding liver disease in NPC1." (PMID 27019000, 2016).
liver disease (continued). "The mechanism by which NPC1 dysfunction leads to liver disease is unknown." (PMID 20886067, 2010). "In the cohort of patients from whom non-HCC tissues were obtained, the underlying liver disease was HBV in three patients, HCV in ten patients, and alcohol in eight patients, with similar NPC1 protein levels observed between these groups." (PMID 40722778, 2025). "In the absence of MGAT5, Npc1−/− mice exhibited earlier liver disease, a 1–2 week earlier progression of the disease phenotype, and increased beam walk latency." (PMID 35563467, 2022). "NPC1 protein levels did not correlate with fibrosis grade, showing that their increase in HCC is a feature of this malignancy rather than of the severity of the underlying liver disease." (PMID 40722778, 2025).
Parkinsonism (12 papers, 2013 to 2025). Characteristic neurologic anomaly resulting from degeneration of dopamine-generating cells in the substantia nigra, a region of the midbrain, characterized clinically by shaking, rigidity, slowness of movement and difficulty with walking and gait. "NP-C is of particular interest in this discussion due to parkinsonism symptoms reported among heterozygeous carriers of NPC1 gene mutations and the association between impaired cholesterol metabolism in the brain and neurodegeneration." (PMID 30369906, 2018). "According to this observation, individuals with heterozygous NPC1 mutations have been found to have an increased risk of parkinsonism or dementia, and several studies have discovered monoallelic NPC1 mutations in cohorts of patients with dementia and brain amyloid deposition." (PMID 41216805, 2025).
Splenomegaly (12 papers, 2013 to 2022). Abnormal increased size of the spleen. "In conclusion, we show elevated G-CSF levels and HSC mobilization in the setting of an Npc1 null mutation and propose that this contributes to splenomegaly in patients with NPC1 disease." (PMID 35007562, 2022). "While accumulation of cholesterol and glycosphingolipids in late endosomes and lysosomes of macrophages with Npc1 loss-of-function may contribute to splenomegaly, the exact cause for this phenotype is unknown." (PMID 35007562, 2022). "We here investigated whether a loss-of-function mutation of Npc1 in hematopoietic cells causes splenomegaly and HSPC mobilization." (PMID 35007562, 2022). "A total of 6/7 had NPC1 mutations, 4/6 had splenomegaly, and 2/6 had hepatosplenomegaly." (PMID 32709131, 2020). "While neurodegeneration is the most severe symptom, a large proportion of NPC1 patients also present with splenomegaly, which has been attributed to cholesterol and glycosphingolipid accumulation in late endosomes and lysosomes." (PMID 35007562, 2022). "Infants with NPC1 usually develop splenomegaly by the age of 3 months and fail to gain weight and grow at the expected rate." (PMID 34944681, 2021). "These patients usually only retain persistent splenomegaly or hepatomegaly until they develop NPC1-related neurological symptoms later in life." (PMID 31861571, 2019). "NPC1 patients exhibit cellular accumulation of cholesterol and sphingolipids which leads to visceral phenotypes of splenomegaly or hepatomegaly, along with a broad range of neurological phenotypes that include cerebellar-related ataxia." (PMID 31861571, 2019). "Approximately 40–50% of NPC1 patients present with splenomegaly during infancy." (PMID 35007562, 2022). "Next, we evaluated the effect on splenomegaly, another typical characteristic of NPC1 pathology." (PMID 34944681, 2021). "While several patients in this cohort had high NP-C SI scores as well as clinical signs associated with NP-C (VSGP and splenomegaly), genetic analyses did not reveal any NPC1 or NPC2 mutations." (PMID 28222799, 2017). "Of note, in this study, we observed reduced spleen weight in control-treated Npc1nih mice compared to wildtype mice instead of characteristic splenomegaly of NPC1 disease, indicating that this model does not recapitulate the spleen NPC1 disease phenotype." (PMID 30666257, 2018). "NP-C needs to be considered in the differential diagnosis of isolated splenomegaly in adults without neurological and neuropsychiatric manifestations and, in the absence of elevated oxysterols, molecular analysis of NPC1 and NPC2 genes should be pursued." (PMID 26937389, 2015).
Pick disease (11 papers, 2013 to 2024). A rare neurodegenerative disorder leading to dementia. "LAMP-1 shuttles between lysosomes, endosomes, and the plasma membrane and binds to cholesterol in association with Niemann-Pick disease type C1 (NPC1) and NPC2 proteins that export cholesterol from lysosomes." (PMID 32999035, 2020). "The Niemann-Pick disease, type C1 (NPC1) gene encodes a transmembrane protein involved in cholesterol efflux from the lysosome." (PMID 24752197, 2014). "The Niemann–Pick disease type C1 (Npc1) gene encodes a large protein that resides in the limiting membrane of endosomes and lysosomes and mediates intracellular cholesterol trafficking via binding of cholesterol to its N-terminal domain." (PMID 25275627, 2014). "Furthermore, we discovered a novel missense variant within Niemann-Pick disease, type C1 (NPC1) that is involved in the hedgehog signaling pathway and intracellular cholesterol transfer." (PMID 32848883, 2020). "A summary of the proteomics data revealed enrichment of 330 proteins in UV light irradiated samples including known cholesterol binding proteins like caveolin-1 (CAV1) and Niemann-Pick disease, type C1 (NPC1), among others 43,44." (PMID 34981045, 2021). "Cathepsin L (CTSL), which primes the filovirus glycoprotein in the endosome, EXT1, which is involved in biosynthesis of heparan sulfate, and Niemann-Pick disease, type C1 (NPC1), showed strong bias against MARV entry." (PMID 26596270, 2015).
atherosclerosis (9 papers, 2010 to 2025). A disease characterized by the build-up of fatty material and calcium deposition in the arterial wall resulting in partial or complete occlusion of the arterial lumen. "Dysregulation of NPC1 has been implicated in atherosclerosis, and its association with the LGF in our study reinforces its role in lipid trafficking as a shared pathogenic mechanism across genetically correlated CVDs." (PMID 41299637, 2025). "In the cardiovascular system, NPC1 has been linked to atherosclerosis." (PMID 39456198, 2024). "Based on these data, it appears that NPC1 gene variants and the imbalance of NPC1 could play an essential role in atherosclerosis and CVD, which are the two significant etiologies of SCD." (PMID 35480314, 2022). "For example, in advanced stage of atherosclerosis, overexpression of NPC1 could reverse plaque vulnerability and increase the risk of SCD." (PMID 35480314, 2022). "Loss/defect in the NPC1 gene has also been shown to promote atherosclerosis in animal models." (PMID 23593294, 2013). "In this study we have presented in vitro and in vivo evidence that cholesterol dyshomeostasis, a common risk factor for NPC-1 and two age-related diseases (i.e., AD and atherosclerosis) may exert its pathogenic effect in part through disruption of the cell cycle." (PMID 23593294, 2013). "Apoe−/− mice, the standard mouse model for atherosclerosis, were crossed with Npc1−/− mice to create a double mutant." (PMID 39456198, 2024). "As one of the key modulators of cholesterol metabolism pathway, NPC1 can affect cellular cholesterol homeostasis, and the imbalanced cholesterol homeostasis is involved in atherosclerosis." (PMID 35480314, 2022). "Some in vivo and in vitro studies also provided evidences that NPC1 gene take part in the development and progression of atherosclerosis." (PMID 35480314, 2022). "In macrophage cell lines, a high level of NPC1 and deletion of NPC1 is primarily responsible for the accelerated atherosclerosis." (PMID 35480314, 2022). "Although the role of oxLDL in neurodegenerative diseases has not been extensively investigated, oxLDL is involved in the pathogenesis of NASH and atherosclerosis, two diseases that share pathological mechanisms with NPC1 disease." (PMID 30666257, 2018). "Deletion of NPC1 in BM-derived cells accelerated atherosclerosis by impairing cholesterol efflux and promoting cellular oxidative stress." (PMID 20955564, 2010). "Nevertheless, it is previously reported that promoter DNA methylation could reduce NPC1 expression and contribute to atherosclerosis progression." (PMID 35480314, 2022). "NPC1 plays a crucial role in the development of atherosclerosis." (PMID 35480314, 2022). "Given the mechanistic overlap between the pathologies of NPC1 disease and of the metabolic diseases atherosclerosis and NASH, the aim of the current study was to determine whether increasing anti-oxLDL IgM autoantibodies reduces NPC1 disease symptoms." (PMID 30666257, 2018). "A connection between the NPC1 and atherosclerosis has been established in several studies." (PMID 20955564, 2010). "The NPC1 cholesterol trafficking pathway could have an impact on the progress of atherosclerosis by above mechanisms." (PMID 20955564, 2010). "Although NPC2 is known to bind cholesterol and promote cholesterol transport, in conjunction with NPC1, its contribution to atherosclerosis has not yet been established." (PMID 32286426, 2020). "In atherosclerosis and NASH, pneumococcal immunization has been shown to ameliorate inflammation and disease severity, suggesting that this treatment may be beneficial to the systemic components of NPC1." (PMID 30666257, 2018).
dementia (9 papers, 2015 to 2025). Loss of intellectual abilities interfering with an individual's social and occupational functions. "Several studies have previously demonstrated an increased risk of dementia and brain amyloid deposition in individuals with heterozygous NPC1 mutations." (PMID 41216805, 2025). "The possible association between heterozygous NPC1 mutations and dementia was also strongly suggested by a mouse model: aged NPC1+/− mouse brains showed cholesterol accumulation, Purkinje cell loss and enhanced tau phosphorylation." (PMID 41216805, 2025). "Additionally, different studies have found heterozygous NPC1 mutations in cohorts of adults with dementia and brain amyloid deposition." (PMID 41216805, 2025). "NPC1 deficiency causes neurodegeneration, dementia and early death." (PMID 31605022, 2019). "However, recent reports have raised concerns on heterozygous NPC1 gene mutation carriers, which historically have been considered as clinically unaffected, occasionally presenting with clinical parkinsonian syndromes or dementia." (PMID 31497485, 2019). "Pathogenic variants of the NPC1 or NPC2 genes yield highly variable phenotypes with a time course that ranges from fetal onset (i.e., hydrops fetalis) to progressive dementia in adults." (PMID 27549128, 2016). "The results of our study demonstrated that heterozygous mutations of NPC1 and NPC2 genes could contribute to dementia plus, at least in a subset of Calabrian patients." (PMID 36140389, 2022). "NPC1 disease commonly manifests through systemic symptoms, such as liver and spleen dysfunction, which precede neurological symptoms (epilepsy, movement disorder, dementia, among others)." (PMID 30666257, 2018).
lysosomal lipid storage disorder (9 papers, 2013 to 2023). An inherited metabolic disorder in which harmful amounts of lipids accumulate in cells and tissues. "The early onset of CD has been recently associated with NPC, a neurodegenerative lysosomal lipid storage disorder wherein the NPC1 (NPC intracellular cholesterol transporter 1) gene that is involved in lipid transport is mutated." (PMID 37554552, 2023). "Niemann-Pick type C1 (NPC1) disease is a lysosomal lipid storage disorder due to mutations in the NPC1 gene resulting in the accumulation of cholesterol within the endosomal/lysosomal compartments." (PMID 37314654, 2023). "Niemann-Pick type C1 (NPC1) disease is a lysosomal lipid storage disorder caused by mutations of the NPC1 gene." (PMID 34481829, 2021). "Niemann-Pick type C1 (NPC1) is a rare lysosomal lipid storage disorder caused by mutations in the NPC1 gene, whose protein mediates the egress of cholesterol from lysosomes/endosomes." (PMID 31178699, 2019). "Patients with the lysosomal lipid storage disorder NPC1 have increased susceptibility to early-onset fistulising colitis with granuloma formation, reminiscent of Crohn's disease (CD)." (PMID 26953272, 2017). "Mutations in the NPC1 gene cause the Niemann-Pick type C1 lysosomal lipid storage disorder that is characterized by multisystem defects including demyelination and progressive neurodegeneration." (PMID 28134287, 2017). "Our results, on the other hand, demonstrated that alveolar lipidosis and other pathological changes were at least as severe in the NPC1 mutant mouse compared to the NPC2 hypomorph mouse." (PMID 23843985, 2013).
Tremor (9 papers, 2009 to 2024). An unintentional, oscillating to-and-fro muscle movement about a joint axis. "To test therapeutic efficacy, we then injected the various viral preparations into the neonatal Npc1nih mice, and here, the NPC1 promoter showed a comparable effect in attenuating weight loss and the tremor phenotype at 10 weeks, as compared to most promoters." (PMID 37371089, 2023). "Npc1−/− mice have a 10–12-week life span, with onset of symptoms (gait abnormalities, tremor and weight loss) beginning at 6–7 weeks of age." (PMID 33738443, 2021). "By 5–6 weeks of age Npc1-/- mice present with progressive neurological symptoms including tremor and ataxia and reach end stage disease by 12 weeks of age." (PMID 27019000, 2016). "Treatment with UDCA also decreased tremor severity and improved motor function in the Npc1 mutant mice suggesting a neurological benefit." (PMID 27019000, 2016).
Crohn disease (8 papers, 2016 to 2025). A gastrointestinal disorder characterized by chronic inflammation involving all layers of the intestinal wall, noncaseating granulomas affecting the intestinal wall and regional lymph nodes, and transmural fibrosis. "Indeed, altered microbial handling was recently demonstratedin vitro and linked to a high penetrance of Crohn's disease in NPC1 patients." (PMID 28008422, 2016). "We identified 4 patients with NPC1 and Crohn’s disease-like intestinal inflammation who received anti-TNF therapy." (PMID 35694196, 2022). "In this respect, Crohn’s disease, a form of inflammatory bowel disease has been reported in some patients with NPC1, suggesting a possible link between N-glycosylation and Crohn’s disease in NPC1." (PMID 35563467, 2022). "Additionally, a high frequency of Crohn’s disease has been observed in NPC1 patients, though the pathomechanisms of Crohn′s disease in NPC1 are different with regard to microbiota changes, at least in the widely used Npc1 mouse model." (PMID 31500175, 2019).